ENSG00000293661 (novel protein, similar to embryonic testis differentiation homolog A)
Gene: Protein-coding gene on chromosome X (135,248,590 to 135,252,011, reverse strand). Ensembl gene ENSG00000293661.
Homologues: Orthologues: mouse 1600025M17Rik (37% identical). Paralogues in human: SMIM10L2B-AS1 (98% identical).